MIR506 (microRNA 506)
Synonyms: hsa-mir-506; MIRN506; mir-506
Gene: MicroRNA gene on chromosome X (147,230,720 to 147,230,843, reverse strand). Ensembl gene ENSG00000207731.
Homologues: Orthologues: macaque mml-mir-506 (74% identical), dog MIR506 (68% identical), dog MIR507A (55% identical), macaque mml-mir-507 (44% identical), chimpanzee ptr-mir-507 (42% identical), rabbit ocu-mir-506 (34% identical). Paralogues in human: MIR513A2 (66% identical), MIR514A1 (48% identical), MIR513B (46% identical), MIR507 (42% identical), MIR514A2 (42% identical), MIR514A3 (42% identical), MIR509-1 (41% identical), MIR514B (35% identical), MIR509-3 (34% identical).
Diseases named in the same sentence as MIR506 in open-access papers:
MIR506 is named in the same sentence as 1 disease in open-access papers, as found by Europe PMC text mining. Sharing a sentence is not in itself a finding about the gene and the disease. The quoted sentences say what the papers report.
tumor (1 paper, 2022). "They discovered that a low expression of MIR506 was associated with increased tumor progression and reduced patient survival." (PMID 36558998, 2022). "Therefore, all of these results demonstrated that MIR506 could act as a tumor suppressor in PDACs by influencing the STAT3-BCL2-BECN1 axis and autophagy-related cell death." (PMID 36558998, 2022).